PLEC (plectin)
Diseases named in the same sentence as PLEC in open-access papers (continued):
Sharing a sentence is not in itself a finding about the gene and the disease.
adenocarcinoma (2 papers, 2013 to 2019). A common cancer characterized by the presence of malignant glandular cells. "The expression of plectin is weak in normal tissues (Panels A (tissue ID # 2053) and B (tissue ID # 2098)) but is in significantly increased to moderate staining in high grade adenocarcinoma tissues (Panels C (tissue ID # 3191) and D (tissue ID # 472))." (PMID 23717685, 2013).
neurodegenerative disease (2 papers, 2022 to 2023). A disorder of the central nervous system characterized by gradual and progressive loss of neural tissue and neurologic function. "Our analysis of the AD interactome indicates that 14-3-3G interacts directly with tau (TAU) and other aggregate proteins, including ankyrin-3 (ANK3), plectin (PLEC), kinesin heavy chain 5C (KIF5C), and hexokinase (HXK1) —all of which play key roles in neurodegenerative-disease aggregation." (PMID 36555098, 2022).
skin disorder (2 papers, 2021). Any deviation from the normal structure or function of the skin or subcutaneous tissue that is manifested by a characteristic set of symptoms and signs. "We summarize the known roles of plectin in keratinocytes and fibroblasts and provide an outlook on future perspectives for plectin-associated skin disorders." (PMID 34685719, 2021). "The role of plectin in skin fibroblasts and its relevance for cutaneous disorders has remained largely unexplored." (PMID 34685719, 2021).
CNS neoplasms (1 paper, 2021). "A potential role of plectin and its isoforms as a biomarker of CNS neoplasms should also be explored." (PMID 34572001, 2021).
digestive system tumors (1 paper, 2025). "Interestingly, plectin demonstrates strong efficacy as a diagnostic target and in targeted drug delivery for PC compared to other plakin family members for other digestive tumors." (PMID 41169522, 2025).
genetic disorder (1 paper, 2023). "EB-PA is a rare genetic disorder characterized by increased skin fragility and PA involving mutations in the ITGB4, PLEC, or ITGA6 genes." (PMID 37033187, 2023).
vascular disorder (1 paper, 2015). A general term used to describe any disease affecting blood vessels]. "To study the mechanisms underlying vascular disorders, we established plectin-deficient endothelial cell and mouse models." (PMID 26519478, 2015).
PLEC also shares sentences with these, for which no sentence is quoted: congenital myasthenia (6 papers); Congenital myasthenic syndromes (3); oral squamous cell carcinoma (3); testicular cancer (3); autosomal recessive epidermolysis bullosa simplex (2); cardiac diseases (2); lung squamous cell carcinoma (2); nephrotic syndrome (2); Obesity (2); ulcerative colitis (2); acute myeloid leukemia (1); amelanotic melanoma (1); Anxiety (1); Arrhythmia (1); arrhythmogenic right ventricular cardiomyopathy (1); Arthritis (1); autosomal recessive generalized intermediate epidermolysis bullosa simplex 5D (1); Becker muscular dystrophy (1); Brain atrophy (1); brain tumors (1); channelopathies (1); chronic intestinal pseudo‐obstruction (1); congenital myopathy (1); depression (1); Desminopathy (1); dilatation (1); distal myopathy (1); Duchenne muscular dystrophy (1); Dystonia (1); epidermolytic hyperkeratosis (1).
A further 31 diseases each share a sentence with PLEC in 1 paper.